HAR1B (highly accelerated region 1B)
Synonyms: HAR1R; NCRNA00065; LINC00065
Gene: Long non-coding RNA gene on chromosome 20 (63,090,806 to 63,102,631, reverse strand). Ensembl gene ENSG00000231133.
Diseases named in the same sentence as HAR1B in open-access papers:
HAR1B is named in the same sentence as 11 diseases in open-access papers, as found by Europe PMC text mining. Sharing a sentence is not in itself a finding about the gene and the disease. The quoted sentences say what the papers report.
glioma (4 papers, 2021 to 2025). A benign or malignant brain and spinal cord tumor that arises from glial cells (astrocytes, oligodendrocytes, ependymal cells). "Inhibition of HAR1B expression has been associated with enhanced migration and invasion in gliomas, and with increased resistance to pazopanib in sarcoma." (PMID 41150811, 2025). "Evidence suggests that HAR1B’s knockdown promotes the migration and invasion of gliomas, while others reported an increased resistance to treatment with pazopanib in sarcoma." (PMID 40004468, 2025). "The genes most significantly coexpressed with HAR1A and HAR1B in lower grade gliomas were analyzed in the publicly available ontology resource Metascape." (PMID 39602392, 2024). "Our results confirmed that HAR1A and HAR1B are negatively correlated with REST expression in pediatric gliomas." (PMID 39602392, 2024). "After determining the expression of HAR1A and HAR1B in the glioma cell lines, we identified their subcellular localization." (PMID 39602392, 2024). "To analyze the relationship between HAR1A and HAR1B with REST in gliomas, we began by correlating their RNA expression in lower grade gliomas and glioblastoma, using the Cbio Portal." (PMID 39602392, 2024). "After showing that HAR1A and HAR1B have positive prognostic roles in lower grade gliomas, we determined possible downstream pathways and upstream regulators of the lncRNAs, using gene ontology." (PMID 39602392, 2024). "Disease-free survival and overall survival rates showed that the expression of DGCR10 and HAR1B are positively correlated with the OS of glioma patients." (PMID 34540695, 2021). "Hence, the objectives of this study are to investigate the clinical significance of REST, HAR1A, and HAR1B expression in pediatric and adult gliomas and their functional roles in key cancer hallmarks (including cell survival, proliferation and migration)." (PMID 39602392, 2024). "In the lower grade glioma dataset, we found that a poorer prognosis of patients correlated with low expression of HAR1A and HAR1B, and with high expression of REST." (PMID 39602392, 2024). "To verify the effects of these lncRNAs on the migration and invasion of glioma cells, we knocked down the expressions of DGCR10, HAR1B, and SNHG18 in glioma cells, and the knockdown efficiency was verified in T98G cells." (PMID 34540695, 2021). "Next, nucleocytoplasmic fractionation was performed to determine the locations of DGCR10, HAR1B, and SNHG18 in glioma cells." (PMID 34540695, 2021). "Similar to the function of these lncRNAs reported in other types of tumors, in our study, knockdown of DGCR10 and HAR1B promoted, whereas knockdown of SNHG18 inhibited the migration and invasion of glioma cells." (PMID 34540695, 2021). "Given that the functions of DGCR10, HAR1B, and SNHG18 are rarely studied in gliomas, the patients from the TCGA database were classified into high- and low-expression groups according to the median expression level of these three lncRNAs." (PMID 34540695, 2021). "Real-time quantitative PCR (RT-qPCR) was carried out to detect the expression levels of DGCR10, HAR1B, and SNHG18 in five glioma cell lines." (PMID 34540695, 2021). "Representative counting of migration and invasion assays after knockdown of DGCR10, HAR1B, and SNHG18 in different glioma cell lines." (PMID 34540695, 2021). "The relative expression level of DGCR10, HAR1B and SNHG18 in different glioma cell lines after knockdown." (PMID 34540695, 2021). "Knockdown of DGCR10 and HAR1B promoted, whereas knockdown of SNHG18 inhibited the migration and invasion of gliomas." (PMID 34540695, 2021). "Following the linear regression analysis of HAR1A, HAR1B, and REST, we determined whether aberrant expression of these lncRNAs and REST impacted glioma patient prognosis, using a Kaplan Meier analysis." (PMID 39602392, 2024).
glioma (continued). "We found that HAR1A and HAR1B have a significant positive correlation in both datasets, HAR1A and REST have a significant negative correlation in both datasets, and HAR1B and REST have a significant negative correlation in lower grade gliomas, but unexpectedly, do not correlate in the GBM dataset." (PMID 39602392, 2024).
glioblastoma (1 paper, 2024). The most malignant astrocytic tumor (WHO grade IV). "To further investigate the clinical relevance of REST and HAR1A/HAR1B expression, we compared the expression of these genes in a publicly available dataset of glioblastoma samples taken from MRI contrast enhancing (CE) tumour core and non-enhancing (NE) tumour periphery regions." (PMID 39602392, 2024).
hepatocellular carcinoma (1 paper, 2021). A malignant tumor that arises from hepatocytes. "Research has confirmed that elevated expression of HAR1B was significant for better OS in hepatocellular carcinoma." (PMID 34540695, 2021).
parathyroid adenomas (1 paper, 2021). "We tested the hypothesis that HAR1B mediates or contributes with menin to modulate the SOX2 expression in parathyroid adenomas." (PMID 34199594, 2021).
soft tissue sarcoma (1 paper, 2022). A malignant neoplasm arising from muscle tissue, adipose tissue, blood vessels, fibrous tissue, or other supportive tissues excluding the bones. "Finally, one study reported that the expression level of the lncRNA HAR1B was higher in pazopanib responders among patients with bone and soft-tissue sarcomas, indicating that HAR1B may serve as a predictive biomarker for response to pazopanib treatment." (PMID 36326232, 2022).
thyroid cancer (1 paper, 2025). "To date, HAR1B has not been specifically associated with thyroid cancer in existing literature; therefore, the present study is the first to report its expression following various treatments in the K1 human thyroid cancer cell line." (PMID 41150811, 2025).
cancer (4 papers, 2022 to 2025). A tumor composed of atypical neoplastic, often pleomorphic cells that invade other tissues. "The precise role of HAR1B still needs to be elucidated; nonetheless, it has been found to be upregulated in cancers and likely induces SOX2 expression in PAd-derived cells." (PMID 39409111, 2024).
tumor (3 papers, 2024 to 2025). "REST, HAR1A, and HAR1B were all differentially expressed between the tumour core and periphery samples." (PMID 39602392, 2024). "Conversely, relative to normal solid tissue samples, REST was upregulated in primary and recurrent tumour samples and HAR1A / HAR1B were downregulated in both primary and recurrent tumours." (PMID 39602392, 2024). "Furthermore, we confirmed that HAR1A and HAR1B expression is comparable intra-tumour cell lines derived from both the GBM core and clinically relevant invasive margin, the latter region reflective of residual disease post-surgery." (PMID 39602392, 2024).
HAR1B also shares sentences with these, for which no sentence is quoted: sarcoma (3 papers); oral carcinomas (2); lung carcinoma (1).